IRF7 (interferon regulatory factor 7)
Diseases named in the same sentence as IRF7 in open-access papers (continued):
Sharing a sentence is not in itself a finding about the gene and the disease.
infection (continued). "However, we found that the expression of IFN-β was upregulated in the CNS of Irf7−/− Ifnβ+/Δluc mice 7 days post-infection compared to WT Ifnβ+/Δluc and Irf3−/− Ifnβ+/Δluc animals." (PMID 37737190, 2023). "After transmutation of IRF7 protein and infection with EV-D68 virus, coimmunoprecipitation showed that IRF7 protein could enrich VP3 protein of EV-D68." (PMID 37125923, 2023). "IRF7 is a positive regulator of IFN-I gene induction downstream of PRRs and the positive feedback loop formed by IRF7-IFN-I allows for the continuous production of large amounts of IFN, which ultimately resists infection by pathogenic microorganisms." (PMID 37251373, 2023). "Lastly, Irf7 gene transcription was robustly induced following infection." (PMID 36851549, 2023). "Therefore, by understanding the role of IRF7 in inflammation, cancer and infection, we can develop the new means to better regulate the function of IRF7 and modulate the immune response in a more precise and effective manner." (PMID 37251373, 2023). "While interferons and interferon-inducible proteins like IRF7, IFIT1, and IFIT3 are primarily associated with antiviral defence, they can also be induced in response to bacterial ligands, contributing to the resolution of the infection." (PMID 37845774, 2023). "In vivo infection of WT and Irf7-/- mice, and in vitro culture of BMDM." (PMID 37251373, 2023). "Both transient transfection of VP3 and infection with EV-D68 virus could reduce the p-IRF7 protein expression by 50%." (PMID 37125923, 2023). "IRF7-dependent parasite elimination was reported in macrophages of the splenic marginal zone during the acute phase of L. donovani amastigote infection in vivo (e.g. 5 to 48 h post-infection) and by a cell line of stromal macrophages in vitro." (PMID 35430587, 2022). "Additionally, KD/KO cells generally showed a decrease in the magnitude of IRF7 transcriptional activation compared to WT cells during the entire course of infection." (PMID 35085371, 2022). "Furthermore, it was recently shown that there was an enrichment in IRF7 loss-of-function variants in patients with life-threatening COVID-19 pneumonia compared to those with asymptomatic or mild infections, implicating IRF7 in anti-SARS-CoV-2 responses." (PMID 35013241, 2022). "Interestingly, most of the analyzed genes, except for IRF-7 and Mx1, showed higher expression upon infection with A12-LH138L as compared to A12-LLV." (PMID 36387381, 2022). "Likewise, we promptly detected co-localization between IRF7 and L. donovani-containing phagosomes at 3 h post-infection in C57BL/6 macrophages, and its accumulation in amastigote-containing compartments at 24 h." (PMID 35154115, 2022). "During E30 infection, genes associated with the type I IFN signaling pathway (Isg15, Mx1, Mx2, Sp100, Ifit1, Ifit3, Ifih1, Irf7, Irf9, guanylate-binding proteins 2 [Gbp2], and Stat1) and defense response to viruses (Ddx58, Ddx60, Zbp1, Oas2, Nlrc5, and Eif2ak2) were significantly upregulated." (PMID 36147849, 2022). "In contrast, IRF7 ∆DBD HCEn cells were impaired for infection-induced promoter activation." (PMID 34389779, 2021). "In addition, knockout of either IRF3 or IRF7 indicated a crucial role of IRF7 as the driver of IFNβ expression in an infection model of DENV." (PMID 33498715, 2021). "Thus, along with the data presented here for HCMV, it is clear that targeting IRF7 expression and/or function during lytic infection is a common theme amongst the herpesvirus family." (PMID 34411201, 2021). "This could be due to the fact that pDCs express basal (or constitutive) levels of IRF7 prior to infection, and therefore, can be considered in an antiviral state." (PMID 34960709, 2021). "Also, IRF7 was highly expressed in each time point at a P < 0.05 (nominal p value), which indicates that it is involved in the whole early infection stages." (PMID 34781942, 2021).
infection (continued). "By focusing on the two macrophage states detected 8 h after the infection, we found the first state to be characterized by the module containing Irf7, Hmga1, Zfp275, and Stat1 that has been previously shown to initiate the inflammatory response to pathogens in an interferon gamma dependent manner." (PMID 34404761, 2021). "Of the IRFs, the mRNAs of IRF3 and IRF7 were significantly induced at 6 h post infection (PI)." (PMID 34389779, 2021). "Inborn errors of TLR3- and IRF7-dependent type I IFN immunity can underlie life-threatening COVID-19 pneumonia in patients with no prior severe infection." (PMID 32972995, 2020). "AR IRF7 deficiency was diagnosed in two individuals aged 49 and 50 years, and AR IFNAR1 deficiency was diagnosed in two individuals aged 26 and 38 years, and none of the four patients had a prior history of life-threatening infections." (PMID 32972995, 2020). "The number of activated astrocytes increased upon infection in both wildtype and Irf-7−/− mice." (PMID 32951602, 2020). "Antiviral activity towards PRRSV and the IBV/PRRSV coinfection displayed upregulation of interferon regulatory factors (IRFs) that included IRF1, IRF4, IRF8, expressed in the PRRSV infection and IRF7 showing up in place of IRF1 in the coinfection in this study." (PMID 33187194, 2020). "Interestingly, we observed a decrease in ISG expression in brachial lymph nodes of xeno mice 2 days following infection, with Ifi44, Irf7, and Stat2 mRNA levels reduced." (PMID 33031404, 2020). "Similarly, Irf7, Isg15 and Stat2 mRNA levels were decreased in axillary lymph nodes of xeno mice 7 days post-infection relative to control mice." (PMID 33031404, 2020). "Plasmacytoid dendritic cells from IRF7-deficient patients produced no type I IFN on infection with SARS-CoV-2, and TLR3−/−, TLR3+/−, IRF7−/−, and IFNAR1−/− fibroblasts were susceptible to SARS-CoV-2 infection in vitro." (PMID 32972995, 2020). "Cytokine expression was induced upon infection in WT and Irf-7−/− in the olfactory bulb." (PMID 32951602, 2020). "After s.c. infection with CHIKV Irf3/7 double deficient mice succumb to the virus while 100% of pDC:Irf7+ mice survive the infection exhibiting no overt clinical symptoms similar to WT mice." (PMID 31031767, 2019). "Interestingly, Irf7 showed by far the highest increase in gene expression 7 days post infection in comparison to the remaining plasma membrane and intracellular localized TLRs." (PMID 29538462, 2018). "Thus, SFSV NSs fail to impair IFN induction in cells where upregulation of IRF7 took place before infection or in cells with physiologically high basic levels of IRF7, such as plasmacytoid dendritic cells." (PMID 30232186, 2018). "The initial sites of CHIKV replication (i.e. the infection site: skin/muscle and muscle) displayed relatively higher viral titers as compared to more distal sites (i.e. the spleen and liver), where virus was barely detectable at 48 h p.i. in pDC:Irf7+ mice." (PMID 29914621, 2018). "Thus, early during infection IRF7 only has a minor contribution to the production of type I and type III IFNs." (PMID 30671054, 2018). "IRF7 was significantly up-regulated in both human and mouse blood after infection (this study)." (PMID 29947965, 2018). "Effector genes including Hif1a (HIF-1α), Irf7 (IRF7), Gzmb (granzyme B) and Gzmc (granzyme C), together with Cd47 as a control, were significantly downregulated in Cd47−/−, less than in WT NK cells upon infection." (PMID 30643501, 2018). "Notably, at 42–72 hr post-infection, pDC:Irf7+ mice displayed significantly reduced levels of DENV titer and RNA in the spleen and plasma compared to Irf3/7 DKO mice." (PMID 29914621, 2018). "Interestingly, IRF3 and IRF7 were only upregulated in head kidney samples after infection with the high virulent reassortant; however, ISG15 and Mx were upregulated in both tissues analyzed." (PMID 30065724, 2018).
infection (continued). "Furthermore, reconstitution of Irf3-/-;Irf7-/- mice with CCR2-DTR bone marrow rescued mice from severe infection, and this effect was reversed by depletion of CCR2+ cells, indicating that CCR2+ hematopoietic cells are capable of inducing an antiviral response." (PMID 29244871, 2017). "Finally, reconstitution of Irf3-/-;Irf7-/- mice with CCR2-DTR bone marrow rescued mice from severe infection, and this effect was reversed by depletion of CCR2+ cells, indicating that CCR2+ hematopoietic cells are capable of inducing an antiviral response." (PMID 29244871, 2017). "For MyD88-dependent TLR signaling, the level of IRF7 remained unchanged throughout 24 hrs of infection in HT-29 cells, which might be affected negatively in RD cells as well, since IRF7 decreased in quantity early after infection." (PMID 27007979, 2016). "In summary, utilization of both stable overexpression and knockdown assays, combined with cutting-edge RNA-seq techniques, provides a powerful method to aid in the elucidation of the function of IRF7 in regulating the host response to pathogen infection in chickens." (PMID 26186542, 2015). "IRF7−/− cells fail to produce IFN-α in response to MVA infection." (PMID 24743339, 2014). "IRF7 was also up-regulated significantly at 24 h post SVCV infection." (PMID 25344771, 2014). "Western blot analysis found that the phosphorylation of Ikk, IκB, and IRF7 could be detected at 24 h post infection (p.i) and 48 h p.i." (PMID 24701034, 2014). "6A suggests that the expression level of IRF7 was higher than that of IRF3 at steady state, which would support the notion that IRF7 could act directly downstream of viral recognition to induce IFNs at the earliest stage of infection." (PMID 24278020, 2013). "In addition to our host model, two in vitro studies have previously reported the simultaneous activation of STATs, IRF-1, IRF-7, and Oct-1 after infection of human monocytes or dendritic cells by Mtb strains." (PMID 22675550, 2012). "Heat map plots of IRF7-controlled genes reveal the divergent responses to the three infections." (PMID 21789257, 2011). "Thus ORF45 through its targeting of the crucial IRF-7 regulated type I IFN antiviral responses significantly contributes to the KSHV survival immediately following a primary infection allowing for progression onto subsequent stages in its life-cycle." (PMID 20485504, 2010). "Notably, MV-induced IRF7 expression in pHMs became markedly augmented at 12–16 h after infection and remained elevated even at 24 h post-infection." (PMID 18617992, 2008). "For example Oas1b, Ifi27, Ifih1 and Irf7 genes were up-regulated at 72 and 96 hr post infection." (PMID 18558011, 2008). "Protein–protein interaction network analysis identified several hub genes (Usp18, Stat2, Ifih1, Jun, Irf7, Rsad2, Ifit1, Mx1) that likely play central roles in coordinating the antiviral immune response and immunometabolic regulation across different phases of infection." (PMID 40867782, 2025). "Furthermore, the comparison of clusters and cell numbers from LGTV-infected WT and Irf7−/− mice 0 and 7 days post-infection reconfirmed our previous findings of prominent differences in the composition of infiltrating immune cells between the four experimental groups." (PMID 37737190, 2023). "However, Irf7−/− mice showed a mild transient drop of body weight on day 8 post-infection." (PMID 37737190, 2023). "We also observed that PRRSV-ADE infection visibly cut down the transcripts of IRF-3, IRF-7, and NF-κB in PAMs in the early stage of infection (after 12–24 h infection), implying that disruption of these three transcription factors may play a crucial part in PRRSV-ADE infection." (PMID 37008366, 2023).
infection (continued). "Indeed, the computed top DEG, typifying each cluster on day 3 in the effector phase of infection, hosted several interferon-induced anti-viral genes (Irf1, Irf7, Ifrd1, Socs1, Socs3, Ifit1, Bst2, and Isg15) as well as genes associated with mature resident Trm cells (Cd69, Nfkbid, Brd2, FosB)." (PMID 35260804, 2022). "Furthermore, infection of U937 cells with m6A-deficient HIV-1 generated from ALKBH5-overexpressed HEK293T cells induced approximately 2-fold higher phosphorylation of IRF3 and IRF7 when compared with control HIV-1." (PMID 33690734, 2021). "The hypothesis that SMAD3 and IRF7 work together in the initial induction of IFNβ is supported by the observations using ΔIFNAR cells, which are capable of the initial IFNβ production following infection but cannot amplify the response." (PMID 34411201, 2021). "However, Irf-7−/− mice showed a mild reduction in body weight at day 8 of infection." (PMID 32951602, 2020). "Next, we compared the host responses between the cell lines upon H6N2 infection, by comparing infected cells to the uninfected cells at each time point of infection, and identified which genes and pathways were potentially modulated by IRF7 in the host response." (PMID 32252379, 2020). "In P. alecto cells, IRF7 mRNA is constitutively expressed and has a more widespread tissue distribution in bats compared to in humans and mice, which may allow bats to respond more rapidly to infection." (PMID 32117225, 2020). "Furthermore, the relatively lower level of upregulation or repression patterns of IFNs upon H6N2 infection despite upregulation of IRF7 could suggest that manipulation of the host immune system by AIV affects the link between the IRF7 and type I IFNs." (PMID 30356848, 2018). "Thus, we have next evaluated whether treatment of IAV-infected mice with LTB4 may have consequences on IRF3, IRF7 and NF-κB activation following infection." (PMID 26444420, 2015). "It is worthy to point out that our result does not exclude the antiviral activity of the IRF-IFN pathway in γHV68 lytic replication, although deficiency of IRF3 and IRF7 or IFNAR did not appear to impact the initiation of γHV68 lytic infection as assessed by plaque assays." (PMID 20686657, 2010). "Finally and IV), IFNβ and IRF7 contribute to the enhancement of lethal infection by IFN-I." (PMID 19325882, 2009). "To understand the CaMKII-dependent regulation of the expression of IFNα and β mRNA early in infection, we focused on IRF3 activation because the expression of IRF7 mRNA is regulated by IFN." (PMID 39601535, 2025). "At 2, 6, and 12 h post-infection (hpi), the transcriptional levels of key genes of cGAS/STING signaling pathway, including cGAS, STING, TBK1, IRF3, IRF7, and IFN-β were evaluated." (PMID 39601590, 2025). "LFBK cells stimulated with transfected poly(dA:dT) (10 μg/mL) to detect IFN-β, IFN-α, IRF7, IRF3, PKR, MX1, ISG56, and ISG15 at 2, 24, and 48 h infection times using qRT-PCR was investigated." (PMID 40500801, 2025). "We found a significant temporal induction of ISGs (for example, MX1, RTP4, IRF7, USP18, TRANK1) in alvORG at day 3 after infection compared to mock-infected samples or nasalALI at day 5 and day 7 compared to day 1 after infection." (PMID 40399606, 2025). "At the same time point, 26544/OG10 infection resulted in increased TLR3 receptor, IRF7 transcription factor, and BCL2 expression." (PMID 40530033, 2025). "Our Irf7−/− mouse model of JEVNSW/22 provides for a more robust viremia, and a slightly higher chance of lethal neuroinvasive infection." (PMID 40295675, 2024). "We assessed BMDMs infected with out panel of M. marinum strains for relative levels of transcript abundance for IFN-β, the transcription factor Irf7, and upstream signalling molecule Rig-I relative to the housekeeping gene GAPDH at 8 hours post infection." (PMID 38394154, 2024).
infection (continued). "Consistently, knockdown of PCGF3 increased the expression levels of ISGs (ISG15, IFIT1, OAS2, MX1 and IRF7) and IFNB1, and decreased the VSV replicates (RNA level and virus titer) after VSV infection." (PMID 39368978, 2024). "We found that the type I interferon (IFN-I)-related genes, DDX60, IFI16, IRF7, ISG15, OAS1, and STAT1, were more highly expressed after Omicron breakthrough infection." (PMID 39835127, 2024). "We identified important genes DE in both our in vitro and in vivo infection models consistent with previous studies, namely, TLR3, IFIH1 (MDA5), SOCS1, OASL, DDX60, STAT1, MX1, CMPK2, LY96 (MD-2), STAT1, STAT2, TRIM25, IRF7, and IFIT5." (PMID 38675946, 2024). "The 17 DEGs upregulated after infection with huH1N1 were shared with the swH1N1 infection (DDX58 (RIG-I), RSAD2 (Viperin), MX2, MX1, OAS1, ANGPTL4, IRF7, ISG15, IFIT1, ISG12(A), DDX60, BST2, IFI44, XAF1, LGALS3BP, RTP4, and IFI6)." (PMID 39247193, 2024). "Irf7−/− mice provide a new model for JEVNSW/22, showing higher viremia levels compared to C57BL/6J mice, and allowing for lethal neuroinvasive infection." (PMID 40295675, 2024). "In vivo infection studies were performed by injecting mice with anti-CCL7 antibody/isotype control, IRF7-siRNA/control siRNA." (PMID 37251373, 2023). "qRT-PCR assay showed that eight antiviral-related mRNA including IRF3, IRF7, IKKβ, TBK1, IFIT1, IFI44, MX1 and ISG15 displayed significantly stronger and quicker response at early infection under 20 °C." (PMID 37627029, 2023). "IRF7 is required for IFN priming at an early stage, which restricts not only the acute infection of herpesvirus families but also chronic gamma herpesvirus infection." (PMID 37638030, 2023). "The Poly (I:C)-induced cells, incubated with high multiplicity of infection (MOI = 3) of the PDCoV, significantly downregulated the expression of RIG-I and TRAF6 and repressed the transcription of RIG-1, IRF7 and IRF3." (PMID 36982944, 2023). "We observed that infection with VSV and SEV increased TBK1 phosphorylation, IRF3 phosphorylation, and IRF7 phosphorylation in NSP9-overexpressed L929 cells compared to control vector-overexpressed cells." (PMID 37854611, 2023). "In our study, overexpression or inhibition of IFI6 upregulated IRF7 expression and downregulated TBK1, LGP2, IFN-α, and IFN-γ expression after infection with ARV." (PMID 38033564, 2023). "Infection with Ectromelia virus (ECTV) decreases the nuclear translocation of NF-κB, IRF3 and IRF7 in murine GM-CSF-derived bone marrow cells." (PMID 37638030, 2023). "After infection of target cells, RNA viruses trigger the activation of downstream IRF3 and IRF7 and NF-κB transcription factors and the production of IFNs." (PMID 35663932, 2022). "On examination of downstream signaling events, interferon (IFN) regulatory factor 3 and IFN regulatory factor 7 (IRF3−/− IRF7−/−) double knockout (DKO) mice experienced lethal infection; whereas, individually, the IRF3 and IRF7 KO models showed >90% survival." (PMID 35301331, 2022). "In this study, we examined the regulatory roles of IRF1, IRF7, and IFN-β in DTMUV replication and the expression profiles of infection-induced genes by constructing two knockout cell lines, KO IRF7 and KO IFNAR1, using CRISPR/Cas9 technology." (PMID 35891486, 2022). "Several CC/CXC chemokines genes as well as antiviral genes, such as IRF7 and ISG15, were among the most upregulated genes throughout infection." (PMID 35812400, 2022). "In the trachea, expression of PRRs, ISGs, IRF7 and STAT1 were moderately up regulated in both groups during the course of infection." (PMID 34918620, 2022). "Moreover, the splenic expressions of zc3h12a and irf7 predicted to be targeted by ssa-miR-146a-5p and nbr-miR-731, respectively, were also significantly affected by infection; particularly, the zc3h12a showed significantly higher expression at 6 h after infection than the control." (PMID 36059498, 2022).